DES (desmin)
Diseases named in the same sentence as DES in open-access papers (continued):
Sharing a sentence is not in itself a finding about the gene and the disease.
tumor (continued). "Tumor cells diffusely expressed SMA (43/43), Desmin (42/43), Caldesmon (40/43), ER (35/43), and PR (32/43)." (PMID 40276735, 2025). "In this patient, the tumor exhibited a high mitotic index (>20/10 HPF), 35% necrosis, and focal desmin positivity, consistent with a high-grade neoplasm." (PMID 41281033, 2025). "Immunohistochemically, the tumor cells are diffusely positive for smooth muscle markers such as SMA and h-caldesmon, whereas desmin typically shows focal expression." (PMID 40002892, 2025). "Immunohistochemically, the tumor cells usually show diffuse cytoplasmic positivity for SMA and variable expression for h-caldesmon and desmin." (PMID 40002892, 2025). "Immunophenotypically, IVL tumor cells express smooth muscle-derived markers (SMA, Desmin, and Caldesmon) and ER and PR." (PMID 40276735, 2025). "The tumor showed epithelioid morphology with brisk mitotic activity, necrosis, and dual myomelanocytic differentiation on immunohistochemistry (HMB-45 and desmin positive)." (PMID 41328270, 2025). "By immunohistochemistry, the tumor cells are frequently positive for EMA, desmin, and CD99, either diffusely or focally." (PMID 38291529, 2024). "Immunohistochemical results showed that the tumor cells positively expressed smooth muscle actin (SMA), anaplastic lymphoma kinase (ALK), CD117, vimentin, but negatively expressed cytokeratin (CK), Desmin and Dog-1." (PMID 39193013, 2024). "Immunohistochemical staining of the spindle and epithelioid cell tumor region revealed that the tumor was positive for CD117 and DOG1, but negative for smooth muscle actin (SMA), CD34, S-100, CD10, HMB45, and desmin." (PMID 38952545, 2024). "Immunohistochemistry showed that the tumor cells were positive for Cyclin D1, smooth muscle actin (SMA), and Desmin." (PMID 39469368, 2024). "Immunohistochemistry showed that tumor cells positively expressed vimentin, SMA, and Desmin usually, and CK, CD68, CD30 and ALK were partially expressed positively, while CD117 and CD34 were usually negative expressed." (PMID 39193013, 2024). "The tumors retained the characteristics of the original tumor, as confirmed through hematoxylin and eosin staining and histochemical analysis using markers such as AE1/3, desmin, S-100, CD34, and vimentin." (PMID 39737254, 2024). "On immunohistochemical examination, tumor cells showed positive immunoreactivity focally to αSMA and diffusely to HHF35 and desmin." (PMID 38704583, 2024). "To delineate the impact of pericyte-specific sGC inactivation on tumor vasculature, we sectioned LLC tumors and stained them with EC-specific marker CD31 and pericyte-specific markers NG2 and Desmin." (PMID 38528180, 2024). "The tumor cells showed positive immunoreactivity for α smooth muscle actin, HHF35, and desmin on immunohistochemical examination." (PMID 38704583, 2024). "Tumor cells were immersed in a dense stromal ECM, as suggested by the relevant expression of Desmin, αSMA, Collagen I, PDGFRα and Vimentin." (PMID 38338669, 2024). "The tumor is positive for high mobility group A2 (HMGA2), estrogen receptors (ERs), a cluster of differentiation 34 (CD34), and desmin immunomarkers." (PMID 39803071, 2024). "The tumor cells showed patchy staining for INSM1 and synaptophysin, but were negative for AE1/AE3, CAM5.2, p40, chromogranin, S100, HMB45, NKX2.2, desmin, CD45 (LCA), CD3, and CD20, with intact INI1 and BRG1 expression." (PMID 39404971, 2024). "The observed diminished protein expression levels of αSMA and Desmin in the PAK1KO tumours suggest a potential impact on the deactivation of cancer-associated fibroblasts, which in turn may lead to the anticipated reduction in angiogenesis within the PAK1KO tumours." (PMID 38067120, 2023). "The notable immunohistochemical characteristics of these tumours are SMA expression and partial expression of desmin, vimentin and ALK." (PMID 36855132, 2023).
tumor (continued). "The immunohistochemical examination is based on positivity for vimentin, desmin, CD34, hormone receptors (estrogens and progesterone, up to 80% of cases), S100, and a low Ki67 (<1% tumor cells)." (PMID 37629707, 2023). "Immunohistochemically, apart from desmin and focal SMA immunoreactivity, tumor cells also displayed multifocal myoD1 and focal myogenin positivity." (PMID 35642345, 2023). "All detectable tumor lesions expressed CD56 (+++, membranous), MYOD1 (+++, nuclear), DESMIN (+, cytoplasmic) and MYOGENIN (++, nuclear)." (PMID 37662907, 2023). "The tumor was highlighted with CD10, showed focal positivity with actin, desmin, and CD68, and had increased Ki67 immunohistochemical staining." (PMID 38247725, 2023). "Consistent with tumor suppression, pharmacological inhibition of TGF‐βR1 abrogated Bmal1‐deletion–triggered tumor fibrosis that showed reduced positive structures of FAP, α‐SMA, DESMIN, PDGFRα, and PDGFRβ." (PMID 37330661, 2023). "Immunohistochemistry analysis of metastatic nodules demonstrated marked mitigation of the FAP+, α‐SMA+, DESMIN+, PDGFRα+, and PDGFRβ+ fibrotic components in TGF‐βR1‐treated Bmal1−/− tumor‐bearing mice." (PMID 37330661, 2023). "Regarding other specific markers, tumours reacted to α-SMA, desmin and SMM, suggesting a smooth muscle origin for both neoplasms." (PMID 37525233, 2023). "Immunohistochemical analysis of metastatic nodules in both lung and liver tissues from CRC and PDAC tumor‐bearing mice showed that metastases in Bmal1−/− mice were enriched in stromal fibroblasts that were positive for FAP, α‐SMA, DESMIN, PDGFRα, and PDGFRβ." (PMID 37330661, 2023). "The tumor can show variable expression of cytokeratins, CD34, desmin, SMA, claudin 1, and muscle‐specific actin and is consistently negative for S100 protein, Kit, and GFAP." (PMID 36074249, 2023). "Histopathological examination of the tumor revealed focal immunoreactivity for Melan-A, HMB-45, desmin, and CD117." (PMID 37041531, 2023). "Immunohistochemical staining for CD34, smooth muscle actin, desmin, myogenin and protein S was performed, with positive staining found only for CD34 in the tumor." (PMID 35906668, 2022). "On the other hand, the most supportive were CAFs derived from the ME mRNA subtype of HNSCC tumour mass, characterised by high expression of EMT markers αSMA, vimentin, and desmin and low gene expression of the TP63." (PMID 35565415, 2022). "A decrease in Desmin+ pericytes and an increase in αSMA+ pericytes resulted in an up to 10 times lower Desmin+/αSMA+ ratio in murine PDAC tumor models and four times lower in human PDAC tumors." (PMID 35626052, 2022). "Positivity for desmin and SMA shows the smooth muscle origin of the tumor and gives a definitive diagnosis." (PMID 35228875, 2022). "Regarding immunohistochemistry, the tumor cells of the uterine mass were positively immunolabeled with smooth muscle actin (SMA), desmin, and CD10." (PMID 36187004, 2022). "Tumor tissues from two GEMMs, KPC and KTC, and three orthotopic models, PANC-1, MiaPaCa-2 and HPAF-II, were stained for CD31(endothelium), αSMA and Desmin." (PMID 35626052, 2022). "Histopathological analysis classified the emerging tumor as RMS, which stained positive for desmin, MYOD, and MYOG." (PMID 36376321, 2022). "Immunohistochemical staining of the postoperative specimen showed Desmin-, Bcl- 2-, and SMA-positive cells, indicating that the tumor originated from smooth muscle cells." (PMID 36324740, 2022). "Immunohistochemically, the tumor stained positively for DICER1, Desmin, and several neurogenic markers." (PMID 36153506, 2022). "Immunohistochemically, the tumor cells showed diffuse and strong positivity for smooth muscle actin (SMA), desmin, and vimentin." (PMID 35719719, 2022). "At the same time, cardiac rhabdoid tumor cells were positive by PAS staining and specifically expressed rhabdoid characteristic actin, desmin, myoglobin, and other immunohistochemical markers but did not express ki-67." (PMID 36337871, 2022).
tumor (continued). "Developmentally, RMS is believed to originate from myogenic progenitors, a concept supported by the expression of myogenic genes such as desmin and myogenin in RMS tumor cells." (PMID 33846547, 2021). "Immunohistochemically, the tumor cells were positive for melanocytic (HMB-45 and Melan-A/MART-1) and myoid (desmin, smooth muscle actin, and muscle-specific actin/all muscle actin/HHF-35) markers." (PMID 34069629, 2021). "In this study, we performed several immunohistochemical stainings, including S-100 protein, SOX-10, CD68, desmin, DOG-1, AE1/AE3, P63 and Ki-67, which are used as ancillary tests for diagnosis of the tumor." (PMID 34243786, 2021). "Immunohistochemically, tumor cells demonstrated membranous positivity for CD99, positivity for Nkx2.2, focal positivity for S100 and negativity for desmin, myogenin, MyoD1, cytokeratin (AE1/AE3), CD31, CD34, CD3, CD20, and CD1a." (PMID 34749732, 2021). "On immunohistochemistry, the tumor cells showed positivity for ALK1 (nuclear), desmin, SMA, CD68, and focal positivity for CD30." (PMID 34249792, 2021). "Further, the tumor didn’t express desmin, ck-pan, α-smooth muscle actin, S-100, myoglobin and CD34, suggesting a dedifferentiated tumor." (PMID 33422117, 2021). "Immunohistochemically, the tumor cells are positive for melanocytic markers (e.g., HMB-45, melan-A) and smooth muscle markers (e.g., SMA, desmin, caldesmon)." (PMID 32867125, 2020). "The tumor vasculature phenotype and function was evaluated by immunohistochemistry for endothelial cells (CD31), pericytes (desmin, α-SMA), hypoxia (pimonidazole) and perfusion (Hoechst 33342)." (PMID 31906502, 2020). "No expression of myogenin, a specific skeletal muscle marker, was observed in tumours, and desmin, a general muscle marker, was heterogeneously and exclusively expressed in RST/A8 H2 tumours." (PMID 33303824, 2020). "Immunohistochemical studies demonstrated that negativity of SMA, desmin, β-catenin, S100, SOX10, AE1/3, EMA, CD117 and CD34 in the tumor cells." (PMID 32164724, 2020). "The remark of this tumor is the immunoreactivity of HMB-45 and muscle markers (desmin, actin, vimentin, keratin, epithelial membrane antigen)." (PMID 32007865, 2020). "Immunobiologically, the tumor diffusely expressed estrogen receptor (ER), progesterone receptor (PR), AE1/AE3, desmin, Wilm’s tumor-1 (WT-1), CD56, and CD99." (PMID 32921307, 2020). "Desmin and MYOD1 positivity of most cells, irrespective of their morphology, indicated the myogenic origin of the tumor." (PMID 33322555, 2020). "Tumor sections from animals treated with either repotrectinib, crizotinib or vehicle were analyzed with Ki-67, CD31 and desmin as markers for proliferation and angiogenesis." (PMID 31852910, 2019). "Histopathological analysis showed an almost completely necrotic tumor with a share of less than 10% viable pleomorphic tumor cells expressing vimentin and CD99 and focal positive desmin." (PMID 31426804, 2019). "Correspondingly, there is a necropsy report of an adolescent domestic canine with an invasive neoplasm in the cranial cavity and hepatic metastases, for which a diagnosis of ERMS was confirmed using immunohistochemical analysis for desmin and myogenin." (PMID 30739231, 2019). "On immunohistochemical analysis the tumor cells were strongly positive for MyoD1, myogenin, and the neuroendocrine cell marker PGP9.5, and weakly positive for desmin, actin, vimentin, CD56, and Syn." (PMID 31870387, 2019). "The MFB tumor cells show immunoreactivity for CD34, desmin, and, variably, with smooth muscle actin (SMA), estrogen receptor (ER)/progesterone/androgen receptor, CD99, B-cell lymphoma 2 (Bcl2), and CD10, and they do not express cytokeratins or p63." (PMID 30989009, 2019). "The tumor cells were positive for cytokeratin (AE1/AE3, CK8/18), EMA, vimentin, desmin, and focally positive for CD56." (PMID 31103034, 2019).
tumor (continued). "In all cases, the tumor cells were immunoreactive for CD34, desmin, smooth muscle actin (SMA), and estrogen receptor (ER) and negative for cytokeratin, p63, CD68, and beta-catenin." (PMID 30989009, 2019). "Histologically, the tumours stained negatively for CD31, DESMIN, MYOD1, MYOGENIN, alpha-SMA and positively for VIMENTIN." (PMID 28982163, 2017). "Immunohistochemically, the tumor cells showed cytoplasmic staining for smooth muscle actin (SMA) and desmin, and nuclear staining for estrogen receptor (ER) and progesterone receptor (PR)." (PMID 28533481, 2017). "Pathological examination of a CT-guided biopsy revealed tumor fragments consisting of bland-looking spindle cells immunoreactive to SMA, desmin, ER, and PR." (PMID 28533481, 2017). "In the current case, the tumor was composed of abundant spindle cells that showed positivity for SMA, desmin, ER, and PR and negativity for HMB-45 and S100, suggesting a pathologic diagnosis of BML." (PMID 28899426, 2017). "On immunohistochemical examination, the tumor cells were positive for alpha-smooth muscle actin (SMA), desmin, CD34, and h-caldesmon, and CD99 was weakly and focally expressed." (PMID 28214470, 2017). "On immunohistochemical examination, the tumor cells express smooth muscle cell markers: HHF35, desmin, smooth muscle myosin heavy chain, h-caldesmon, and recently transgelin." (PMID 27633779, 2016). "The combination of IHC tests including LCA, vimentin, desmin and CD99 is useful to primarily assess the phenotype of the tumor cells." (PMID 27756397, 2016). "We also performed immunocytochemistry for desmin and SMA to confirm the primary cell line STS39 was representative of the original tumor it was derived from." (PMID 26952093, 2016). "After exposure to the tumor microenvironment, MSCs expressed TAF markers including Tn-C, α-SMA, desmin, and fibroblast marker Collagen I, indicating their differentiation towards TAFs." (PMID 27531897, 2016). "Prior to the analysis, we demonstrated the urothelial origin of the tumor cells through hematoxylin-eosin (H&E) staining and immunohistochemistry (IHC) analysis for cytokeratin (CK) 7, pan-CK, Ki-67, CK20, and desmin." (PMID 27438149, 2016). "In our case, immunohistochemistry revealed that the tumor cells were positive for α-SMA, desmin, and vimentin." (PMID 26380169, 2015). "Immunohistochemical staining had shown that the tumour was strongly positively stained for smooth muscle actin, calponin, and CD44 and focally positive for desmin." (PMID 26640482, 2015). "Immunohistochemical staining revealed that the tumor cells were differentiated into fibroblastic and myofibroblastic, which are strongly positive for vimentin and SMA, and weakly positive for desmin and CD34." (PMID 26303928, 2015). "Immunohistochemistry demonstrated that the tumor cells were positive for α-smooth muscle actin (α-SMA), desmin, and vimentin." (PMID 26380169, 2015). "Immunohistochemical analysis revealed that the tumor cells expressed HMB45, Melan-A, SMA, HHF35, Desmin, and pathogenesis-related protein, and were negative for all other markers tested." (PMID 25621681, 2015). "PEComa is a family of rare tumours consisting of perivascular epithelioid cells (PECs) that coexpress melanocytic (HMB45 and/or melan A) and smooth muscle markers (actin and/or desmin)." (PMID 25821471, 2015). "Apart from promoting tumor growth, IGF1R and INSR overexpression also enhanced angiogenesis indicated by higher vessel density and increased number of desmin-immunoreactive pericytes." (PMID 24809298, 2014). "Some tumour cells were positive for CD117 (c-kit), whereas all of them were negatively stained for CK7, CK20, Desmin, and CD34." (PMID 24587922, 2014). "The tumor cells were diffusely positive for CD99, desmin, and WT1 and showed scattered focal positivity for cytokeratin." (PMID 24406431, 2014).
tumor (continued). "To further investigate tumor vasculature, we stained lung tissues with different markers such as CD31 and desmin to stain endothelial cells and smooth muscle cells respectively." (PMID 23627488, 2013). "Whilst all the spindle cells within the tumour expressed CD34, AR, ER, BCL2, and CD10, only those within the myofibroblastoma expressed desmin and only those within the lipomatous areas expressed S100." (PMID 24459597, 2013). "The diagnosis of an EGIST in the present case was in accordance with the histological and immunohistochemical criteria; the tumor was epithelioid-type, and was immunopositive for CD117 and desmin." (PMID 23420829, 2013). "The fluorescence of tumor stroma after fluorescent dye injection in the CAM vasculature confirms that the vessels are functional and the detection of desmin positive pericytes suggests vessel stabilization." (PMID 24040391, 2013). "Desmin and VWF double staining commonly showed co-localisation to blood vessel walls in the tumor tissue and in the normal mucosa from some stage III and IV tumors, but not from early stage tumors." (PMID 22141345, 2011). "On immunohistochemical staining, the tumor expressed focal smooth muscle actin (α-SMA) and vimentin, while a small number of tumor cells were also weakly positive to HHF-35, desmin and S-100 stains." (PMID 20205848, 2010). "Immunohistochemically the tumor cells strongly expressed Vimentin, MyoD1, SMA and CD99, being negative for the remaining antibodies tested, including Myogenin and Desmin." (PMID 20701800, 2010). "Microvascular channel formation is specific to tumor vasculogenesis and is featured by the small, un-orderly arrangement of microvessels that we depict through α-SMA, desmin and VEGF staining." (PMID 19352430, 2009). "Because vessel structure and function can be affected by association with perivascular cells, we next analyzed coverage of the tumor vessels by NG2- and desmin-positive pericytes." (PMID 19352490, 2009). "Immunohistochemically, the tumor cells of both phenotypes in all three lesions stained for melanocytic (HMB-45 and Melan-A/MART-1) and myoid (desmin, smooth muscle actin, and muscle-specific actin/all muscle actin/HHF-35) markers." (PMID 18053181, 2007). "The IHC staining was positive for CD99 and FLI-1 (in >50% of tumor cells) and negative for AE1/AE3, INI-1 loss, WT1, desmin, myogenin, BCOR, TLE-1, CD45CLA, and synaptophysin." (PMID 41230381, 2026). "Immunohistochemistry plays a pivotal role in diagnosis, with tumor cells typically expressing CD34, which highlights fibroblastic and spindle cell components, and desmin, indicative of myogenic differentiation, while showing variable S100 expression limited to adipocytic or neural elements." (PMID 41527615, 2025). "The final pathology report came back as: 20mm well-defined submucosal bland spindled tumour, which is positive with muscle marker (Desmin), negative with S100 and CD117." (PMID 40955214, 2025). "The negativity for S100 and Desmin excludes other neurogenic or muscular differentiation neoplasms, while the absence of mitosis and necrosis confirms the benign nature of the tumor." (PMID 41010284, 2025). "Immunohistochemical analysis showed that the tumor cells of inflammatory myofibroblastoma strongly expressed vimentin, partially expressed desmin and ALK, and showed no expression of CD34 and CD117." (PMID 40548121, 2025). "PEComa is a mesenchymal origin tumor with unique immunophenotypic features, and its typical pathological features are the expression of both melanocyte markers (HMB-45, Melan-A) and smooth muscle markers (SMA, Desmin)." (PMID 41551141, 2025). "Most tumor cells are spindle-shaped, and the immunophenotype is positive for SMA, Desmin, and CD34." (PMID 41137250, 2025). "Immunohistochemistry showed that tumor cells were AE1/3 (+), S-100 (–), Desmin (–), WT1 (–)." (PMID 40034204, 2025).